CTLA4 (cytotoxic T-lymphocyte associated protein 4)
Diseases named in the same sentence as CTLA4 in open-access papers (continued):
Sharing a sentence is not in itself a finding about the gene and the disease.
tumor (continued). "Thus, lack of DCs limited tumor-specific T cell priming, leading to development of resistance to PD-L1 and CTLA-4 blockers-based therapies in experimental murine tumor models." (PMID 29482595, 2018). "Antibodies to CTLA-4 may act to facilitate tumor entry and alter the movement in tumors, rates of egress." (PMID 30542345, 2018). "Moreover, combined radiotherapy with anti-CTLA-4 treatment induced abscopal effects (shrinkage of tumour lesions outside of the target region of radiotherapy), in this case consisting of complete regression of metastases at different sites." (PMID 29875199, 2018). "Interestingly, in mice depleted of CD8 T cells prior to tumor implantation the combination of anti-CTLA4 and RT was ineffective." (PMID 29725089, 2018). "Thus, numerous studies have shown that CTLA-4 and PD-1 have an important role in mediating immune evasion in the tumor microenvironment." (PMID 28866656, 2018). "What then is the primary mechanism of anti-CTLA-4 antibody induced tumor rejection?" (PMID 29713453, 2018). "Interestingly, anti-tumor response was heightened significantly when SIRPα-Fc-CD40L was combined with antibody blockade of CTLA4, PD1, or PDL1." (PMID 30400822, 2018). "In this situation, blockade of CTLA-4 further promotes tumor regression." (PMID 30100909, 2018). "However, CSF1R blockade in combination with either an antibody against PD-1 or CTLA-4, except for gemcitabine, led to improved tumor regression, suggesting that CSF1R blockade induced reduction of TAMs and enabled response to ICB." (PMID 29482595, 2018). "Therefore, additional studies are required to address this undetermined synergistic anti-tumor activity of combining RT with CTLA-4 blockade." (PMID 30115069, 2018). "CTLA-4 is highly expressed on tumor-infiltrating lymphocytes in lymphoid malignancies." (PMID 30040869, 2018). "Although the highly effective counteraction of Tregs and immune tolerance by a-CTLA4-TGFβRII was sufficient to inhibit tumor growth, this might have obscured any potential value of combination therapy with a-PD1 during the course of the experiment." (PMID 29467463, 2018). "T cells express CTLA-4 that would be cytotoxic to tumor cells." (PMID 30366424, 2018). "The combination regimen of either anti-CTLA-4 Ab or anti-PD-L1 Ab with pegzilarginase induced greater anti-tumor activity than either IO monotherapy, including an increase in complete responses (CRs) in anti- PD-L1 Ab studies (37.5% CRs in combination arm vs. 0% in anti-PD-L1 Ab arm)." (PMID 30400835, 2018). "Together these results lend support to our gene signature as a clinically relevant gene expression signature of a ‘hot’ immunogenic tumor in Treg-enriched patients who may be more likely to respond to checkpoint blockade therapies targeting PD-1 and or CTLA-4." (PMID 29928512, 2018). "DE50 values of the tumor in anti-PD-1 or anti-CTLA-4 treated mice were lower than control mice." (PMID 29348598, 2018). "Programmed Death Receptor 1/Programmed Death Receptor Ligand 1 (PD 1/PD-L1) and Cytotoxic T Lymphocytes Antigen 4 (CTLA-4) inhibitors are agents able to target specific pathways related to immune-response which are often hyper-activated by tumor cell interaction." (PMID 30450335, 2018). "However, it was recently proposed that the restoration of CTL activity and subsequent antitumor immune response in pre-clinical models rather resulted from anti-CTLA-4-mediated depletion of immunosuppressive regulatory T cells (Tregs) in the tumor bed." (PMID 30487462, 2018). "CTLA-4 and PD-1 are not the only immunoregulatory receptors associated with anti-tumor T cell immunity." (PMID 30319637, 2018). "Treatment of CTLA-4 expressing tumor cell lines with recombinant forms of the CTLA-4 ligands CD80 and CD86 induced caspase-8-dependent apoptosis and the level of apoptotic tumor cells was reduced by soluble CTLA-4 and anti-CTLA-4 single-chain variable fragment antibodies." (PMID 29682176, 2018).
tumor (continued). "Taken together, targeting the cell intrinsic and extrinsic mechanisms of the CTLA-4 pathway with neutralizing antibodies can be considered as a requisite approach to enable other therapeutic strategies aimed to promote or restore tumor-specific T cell immune responses in patients." (PMID 29617360, 2018). "A “checkpoint inhibitor” such as anti-CTLA-4 and anti-PD/PD-L1 binds with these co-inhibitory checkpoint molecules and counter-inhibits the downregulation of T effector function, hence reinstating anti-tumour activity." (PMID 30413094, 2018). "In summary, PD-1 and CTLA-4 blockade may enhance the anti-tumor activity of NK cells both directly and indirectly, via other immune cells such as tumor-specific T cells." (PMID 30250471, 2018). "Anti-CTLA-4 mAbs-induced similarly robust tumor rejection in young (6–7-week-old) adult mice." (PMID 29463898, 2018). "In the future treatments, we speculate that the application of several new drugs which target immune checkpoints such as PD-1, PDL-1 and CTLA4 may enhance the host anti-tumor immune response as reported." (PMID 30241515, 2018). "The clinical response to anti-PD-L1, anti-PD-1, or anti-CTLA-4 targeted therapies can vary in different tumor types, and much effort has been directed toward finding predictive biomarkers to help identify patients who will derive the most benefit from these therapies." (PMID 30057891, 2018). "In particular, the combination of concurrent PD-1 and CTLA-4 blockade holds considerable promise, since PD-1 contributes to T-cell exhaustion primarily in peripheral tissues and within the tumor microenvironment, and CTLA-4 inhibits at earlier point in T-cell activation." (PMID 30384507, 2018). "Similarly, EGFR pathway activation has been found to be correlated with development of immunosuppressive microenvironment represented by upregulation of PD-1, PD-L1, CTLA-4, and multiple tumor-promoting inflammatory cytokines." (PMID 30294272, 2018). "The U.S. FDA approved Bristol-Myers Squibb’s anti-CTLA-4 treatment, called ipilimumab, for metastatic melanoma in 2011; ipilimumab showed a durable and potentially curative efficacy in potentiating tumour regression, with a higher complete response rate than in previous reports." (PMID 29848327, 2018). "Therefore, they combined immune-potentiating strategies via the administration of CTLA-4-blocking antibodies to lower the threshold for T-cell activation and obtained a better immune response, finally leading to increased tumour protection." (PMID 29386009, 2018). "Therefore, CTLA-4 blockade probably removes inhibitory signals in the costimulatory pathway, resulting in the enhanced rejection of the tumour cells." (PMID 29848327, 2018). "In mice, CTLA-4 expression was evaluated in peripheral blood mononuclear cells (PBMCs), draining lymph nodes (LNs), and tumor-infiltrating lymphocytes (TILs) by flow cytometry 10 days after tumor challenge." (PMID 29576375, 2018). "Additionally, reduced CD25, CD73, and CTLA-4 on tumor-infiltrating CD4+ T cells in both age groups suggest reduced Treg-mediated suppression within IL-2/CD40-treated tumors." (PMID 30560130, 2018). "Thus, it has been demonstrated that CTLA-4 blockade results in a significant increase of tumor-infiltrating CD8+ T cells." (PMID 29494517, 2018). "The mechanisms of cancer immune escape mainly include: reducing the expression of tumor antigens; increasing co-inhibitor expression (e.g., PD-L1, CTLA-4); secreting suppressive cytokines (e.g., TGF-β and IL-10); and lastly orchestrating an immunosuppressive microenvironment." (PMID 30250823, 2018). "The authors reported that IFN-γ expression was still able to induce resistance when PD-L1 was deleted, but when IFN-γ's receptor IFNGR and the receptor for Type I IFNs IFNAR were knocked out on tumor cells, exhausted T cells were significantly reduced and response to RT and anti-CTLA4 was enhanced." (PMID 30766539, 2018).
tumor (continued). "Therefore, AGEN1884, by virtue of its IgG1 Fc region, has the ability to bind to CTLA-4 on Treg cells within the tumor and co-engage FcγRs on effector cells to mediate their selective depletion." (PMID 29617360, 2018). "CTLA-4 blockade may also take effect at the tumor site as exhausted CTLA-4-expressing T cells and Tregs can accumulate within the tumor microenvironment." (PMID 29644214, 2018). "It was shown that the combination of PTT and CTLA-4 antibody could completely inhibit the growth of distant tumor and lung metastasis." (PMID 30406152, 2018). "The classical checkpoint blockade hypothesis has suggested that anti-CTLA-4 mAb induces tumor rejection by inducing activation of naive T cells in the lymphoid organs." (PMID 29463898, 2018). "Tumor microenvironment immune types I cancer was characterized as sensitive to anti-CTLA-4 therapy." (PMID 32793247, 2018). "Notably, immune responses following CTLA-4 blockade with ipilimumab not only execute their program systemically in secondary lymphoid organs contributing to reinstating tumor immunosurveillance but also are directed at sites where microbiota are abundant." (PMID 29482595, 2018). "Blockage of CTLA4 increases antitumor response and attenuates tumor progression." (PMID 29682521, 2018). "A recent study has demonstrated that a CD73-blocking antibody increases the anti-tumor effect of CTLA-4/PD-1 inhibition, suggesting that the combination of such treatments could be beneficial in clinical settings." (PMID 30135516, 2018). "Induction of an effective T-cell response may be insufficient due to tumor evasion strategies other than PD1 or CTLA-4." (PMID 29678194, 2018). "Consequently, combination of intratumoral NDV with systemic PD-1 or CTLA-4 blockade led to improved local and abscopal tumor control and overall survival." (PMID 29983890, 2018). "In subsequent investigations, we examined the epigenetic modifications in tumor and normal tissues and found that the CpG motifs in the promoter regions of PD-1, CTLA-4, and TIM-3 genes were hypomethylated in tumor tissue, compared with normal tissue, but not significantly in LAG-3 promoter." (PMID 29983831, 2018). "Importantly, in preclinical studies on a mouse model, the use of anti-PD-1 or anti-CTLA-4 mAbs together with CVA improved anti-tumor response." (PMID 30413032, 2018). "Blockade of CTLA-4 using the monoclonal antibody ipilimumab improves anti-tumor activity." (PMID 30250823, 2018). "This advanced disease model is more akin to metastatic human tumours, and is considerably more immunosuppressive with heavier tumour burden and increased immunosuppressive factor expression in the tumour microenvironment (PD-1, PD-L1, CTLA-4, TGF-β, CD105, and VEGF)." (PMID 30410056, 2018). "Moreover, in tumor cells, CTLA-4 protein localised in the membrane, cytoplasm or both in a scattered pattern." (PMID 29682176, 2018). "Similarly, a range of RT doses, combined with anti-CTLA-4, have led to reduced primary tumor growth of the irradiated tumor, including 12–20 Gy × 1, 12 Gy × 2, 8 Gy × 3, and 6 Gy × 5; however, only the fractionated regimens also led to abscopal effects." (PMID 30360504, 2018). "Along the way, researchers have assumed that the regulation of immune checkpoint pathways might have an impact on anti-tumor immunity, thereby leading to the successful administration of CTLA-4/PD-1-blocking antibodies to treat many types of cancers." (PMID 30135516, 2018). "Finally, combination of M7824 with anti-CTLA4 significantly decreased tumor volume in the B16 model." (PMID 30400835, 2018). "When immune checkpoint inhibitors, such as anti-CTLA-4 and anti-PD-1, are combined with RT, this stimulates release of tumor antigens, which activates the immune response and mounts a coherent immune assault against the tumor." (PMID 30486519, 2018).
tumor (continued). "Here we set out to 1) determine whether OncoVEXmGM-CSF and anti-CTLA-4 combination treatment elicits a durable anti-tumor memory response and 2) to identify tumor-specific MHC-I epitopes generated by the treatment." (PMID 30400822, 2018). "In comparison, treatment with PLGA-ICG-R837 or CTLA-4 antibody could only slightly slow the growth of secondary tumor and the metastasis could still be observed apparently." (PMID 30406152, 2018). "Nonetheless, patients with metastaticmelanoma might need a rapid response, especially in presence of large tumor burden.In the adaptive immune response, CTLA-4 activation mediates an earlier phase thanPD-1 one." (PMID 29552325, 2018). "Although the relevance of Tregs is mostly considered during initial T cell priming whereby Tregs inhibit T cell activation by CTLA-4 intervention, there is also evidence that Tregs apply other mechanisms to enforce peripheral tolerance in the tumor environment." (PMID 29032503, 2018). "Tumor growth in preclinical mouse models was analysed after targeted desialylation of tumors combined with checkpoint inhibitors including anti-PD-1 and anti-CTLA-4 antibodies." (PMID 30400822, 2018). "However, it has also been shown that enhanced tumour therapy mediated by the anti-CTLA-4 antibody is dependent upon interaction with both Tregs and T-effectors in order to elicit full tumour protection." (PMID 29570634, 2018). "Moreover, treatment with a combination of viruses expressing either an anti-CTLA-4 blocking antibody or GM-CSF resulted in complete tumor regression." (PMID 30619273, 2018). "Results showed that combination of PTX and SGP restored the exhausted antitumorigenic immune cells (especially Tc) via inhibiting the expressions of immune checkpoints (PD-1 and Tim3), while PTX alone even evidently increased that of CTLA-4, suggesting a recovered tumor immune surveillance." (PMID 30619178, 2018). "Therefore, blocking the ligand binding site or reducing the expression of PD-1 and CTLA-4 should stimulate the proliferation of immune cells and induces or enhances the anti-tumor immune response." (PMID 30564277, 2018). "Following such observations, Łuksza and colleagues designed a neoantigen fitness model, which is based on the likelihood of neoantigen presentation by HLA molecules and subsequent T cell recognition, to predict clinical outcome of tumor patients after anti-CTLA-4 therapy." (PMID 29494517, 2018). "A recent study, which assesses the therapeutic effects of the CTLA-4 antibody ipilimumab, found ipilimumab might increase frequencies of tumor-infiltrating T cells expressing LAG-3 in metastatic melanoma patients." (PMID 30603054, 2018). "Suppression of T cell functions occurs through downregulation of MHC molecules and co-stimulatory ligands, with upregulation of inhibitory receptors like programmed cell death protein ligand 1 (PD-L1) on tumor cells and cytotoxic T-lymphocyte antigen-4 (CTLA-4, CD152)." (PMID 29854318, 2018). "Inactivation of EZH2 in this context produced a synergistic effect with CTLA-4 and IL-2, suppressing tumor growth, which suggests that EZH2 expression may serve as an immune escape mechanism during immunotherapy." (PMID 30497521, 2018). "Notably, however, the number of NR2F6-expressing TILs was highly correlated to the abundance of PD-1 and CTLA-4-expressing TIL as well as PD-L1 expression on tumor cells." (PMID 29670099, 2018). "Tumor specific effector immune responses are boosted with CTLA4 blockade and tend to be durable." (PMID 29973204, 2018). "Two of the most encouraging approaches involve the blockade of immune checkpoints through checkpoint inhibitors, such as cytotoxic T-lymphocyte-associated antigen-4 (CTLA-4) antibodies or PD1 inhibitors and vaccine therapy, which evokes specific immunity against certain tumor-related antigens." (PMID 30416904, 2018).
tumor (continued). "This evidence suggests that CD5, along with PD-1 and CTLA-4, may be a potential target to specifically modulate T cell Ca2+ mobilization in an immunosuppressive tumor setting." (PMID 29701673, 2018). "Co-stimulating the immune system with a shower of tumor antigens via cryosurgery in the presence of a “primed” immune system pre-treated with CTLA-4 and PD-1 combined therapy would theoretically result in a synergistic effect of local tumor and distant metastases regression, or abscopal effect." (PMID 29644213, 2018). "Importantly, the anti-PD1/anti-CTLA4 treatment in combination with PLX3397 completely blocks the tumor expansion and even regresses the established tumors by 15%." (PMID 29670880, 2018). "Further, in the case of poorly immunogenic tumors, which have a limited endogenous immune response, the combination of CTLA-4 antibody with a vaccine has the potential to establish an immune response to hinder tumor growth and lead to tumor regression in certain cases." (PMID 28866656, 2018). "Some studies have suggested that CTLA-4 expression in the tumor microenvironment may be important for prognostic implications." (PMID 29672601, 2018). "However, the combination of i.t. anti-mesothelin immunotoxins with systemic anti-CTLA-4 induced tumor regression in the majority of the mice, supporting the idea that the combination of the two outperforms each treatment alone." (PMID 30441807, 2018). "It is assumed that anti-CTLA-4 antibodies cause tumor rejection by blocking negative signaling from B7-CTLA-4 interactions." (PMID 29472691, 2018). "Additionally, in both PD-1 and CTLA-4 promoters, H3K9me3 binds significantly weaker than H3K27me3 in tumor tissues." (PMID 29983831, 2018). "Since young mice expressed higher levels of CTLA-4, recapitulating a feature of adult tumor-bearing mice, we treated perinatal human CTLA4 knock-in (Ctla4h/h) mice with control human IgG-Fc, anti-CTLA-4 mAb Ipilimumab, L3D10, anti-PD-1, anti-PD-1 + Ipilimumab or anti-PD-1 + L3D10, respectively." (PMID 29463898, 2018). "Initially, it was suggested that upon binding CTLA-4 the monoclonal antibody blocks its inhibitory effect on both effector and regulatory T cells, thereby increasing effector T cell activity sufficient for induction of tumor regression." (PMID 29032503, 2018). "Increased expression of PD-1, PD-L1 and CTLA-4 were found in stromal/immune cells of group II as compared to Group I. Expression of these immune markers showed significant correlation with poor tumor differentiation, tumor invasion and patient outcome (p<0.05)." (PMID 30400835, 2018). "Currently, CTLA-4 mAbs are been tested in phase I-III trials in a variety of tumor types." (PMID 29928478, 2018). "We propose that when the host’s immune system has been “primed” with combined anti-CTLA-4 and anti-PD-1 adjuvants prior to cryosurgery, the preserved cryoablated tumor antigens will be presented and processed by the host’s immune system resulting in a robust cytotoxic CD8+ T-cell response." (PMID 29644213, 2018). "CTLA-4 is a negative regulator of T-cell activation, which inhibits anti-tumor immune responses." (PMID 30250823, 2018). "Across all studied mouse models, CTLA-4 expression appeared higher in the tumor and was largely restricted to CD4+FoxP3+ Treg cells (mean expression 68.3%), relative to CD4+FoxP3− effector (CD4+eff) T cells (10.2%, p < 0.0001) and CD8+ T cells (5.4%, p < 0.0001)." (PMID 29576375, 2018). "Since PD-1 is expressed not only on immune cells but also on tumor cells, the superior clinical activity and safety profile of anti-PD-1 compared with anti-CTLA-4 therapy may be due to the additional effects of anti-PD-1 on targeting tumor-intrinsic signaling." (PMID 30105035, 2018). "In addition, T-cells in the tumor microenvironment express CTLA-4 so that blockade releases this localization which enables them to even enter immune privileged microenvironments." (PMID 30542345, 2018).